IL33 (interleukin 33)
Diseases named in the same sentence as IL33 in open-access papers (continued):
Sharing a sentence is not in itself a finding about the gene and the disease.
infection (continued). "Compared to RV-A (RV-1B) infection, RV-C (RV-C15) infection induced higher BALF eosinophilia, mRNA expression of IL-5, IL-13, IL-25, Muc5ac and Gob5/Clca, protein production of IL-5, IL-13, IL-25, IL-33 and TSLP, and expansion of ILC2 in naive and HDM-immunized BALB/c mice." (PMID 35386658, 2022). "The apoptotic caspases 3 and 7 cleave human IL-33 at amino acid D178 and/or the D175GVD178 consensus site, generating two inactive fragments unable to bind ST2, although a recent study argues against this conclusion in an infection model." (PMID 36291105, 2022). "This is crucial for the clearance of intestinal helminths as mice that lack IL-33 are not able to effectively cope with the infection, likely due to defects in the T cell and ILC2 compartments." (PMID 35950748, 2022). "We demonstrated that IL-33 induced an antiviral signature in MCs but rather than providing protection against HRV infection, IL-33 increased the infection of MC by HRV by causing upregulation in ICAM1, the receptor used by HRV16 for cellular entry." (PMID 36366528, 2022). "IL-33 concentration dependently increased IFNB1 in the absence of infection while in the presence of both IL-33 and HRV16 there was a further significant increase in expression of IFNB1 and IFNLI." (PMID 36366528, 2022). "Heterologous infection did not increase IL-33 mRNA levels in CD45-EpCAM- cells or CD45+F4/80+ macrophages." (PMID 36032072, 2022). "The evaluation of IL-33 protein showed, interestingly, an increase on day 3 after infection as compared with non-infected lungs, thus suggesting an inducible behavior of the cytokine." (PMID 35327516, 2022). "IL-33 polarizes the innate and adaptive type two immune response by promoting the activation of ILC2, eosinophils, Th2 and the IL-8-induced migration of neutrophils to the sites of infection." (PMID 36359220, 2022). "However, the activation role of IL-33 on antiviral CD8 T cells, with consequent possible elimination of the virus in long-lasting infections, is known." (PMID 35327516, 2022). "IL-33, which was already prominently expressed in naïve ear skin, was also not upregulated upon infection with L. major in either mouse strain." (PMID 35894051, 2022). "Our observations show that during infection, the absence of the IL-33/ST2 pathway influences the pulmonary immunological response, mainly inducing the Th17 response." (PMID 34324507, 2021). "However, during infection with LCMV or MCMV, IL-33 promotes the expansion of NK cells and T cells and their production of IFN-γ, and loss of the IL-33R results in a delay in viral clearance." (PMID 33929319, 2021). "Infection i.p. with 2 × 105 tachyzoites of the non-replicating CPS strain did not cause parasite-induced host cell lysis and failed to elicit detectable IL-33 at 1 or 5 days post-infection (dpi) (data not shown)." (PMID 33929319, 2021). "In IL-33- and ST2-KO mice, most mice died within 2 days after infection." (PMID 34638904, 2021). "The results showed that sera from IL-33-KO and ST2-KO mice had weaker bactericidal activity than those of WT mice, and the remnant bacterial numbers of the KO group was five times greater than in the WT group after in vitro infection." (PMID 34638904, 2021). "Concomitantly, IL-33 inhibits the differentiation of IL-17A-producing CD4+ T cells, which have the potential to reverse the negative effect of IL-33 during infection." (PMID 33654214, 2021). "IL-33 drives ILC-cell-dependent recruitment of CCR2+ inflammatory monocytes, which resemble the TipDCs (TNF and iNOS-producing dendritic cells) previously shown to be important for control of infection." (PMID 33929319, 2021). "We were unable to detect any significant differences in IL-33 levels in either human cohort, suggesting that this cytokine is not a good biomarker of infection." (PMID 34662329, 2021).
infection (continued). "In support of this hypothesis, a previous study demonstrated that high levels of IL-33 were released and ST2 receptors signaling pathways were highly triggered during infection of epithelial airway tissues, provoking further pyroptosis." (PMID 34608167, 2021). "Thus, the IL-33/ST2 pathway sustained the Th2 immune response contributing to eosinophil activity, tissue damage and parasite tropism during infection by T. canis in mice." (PMID 34324507, 2021). "GAS infection induced IL-33 expression in wild-type (WT) C57BL/6 mice, whereas the IL-33- and ST2-knockout mice had higher mortality rates, more severe skin lesions and higher bacterial loads in the air pouches than those of WT mice after infection." (PMID 34638904, 2021). "Mice in the model, IL-33, and ST2 groups showed obvious tissue damage 24 h after infection." (PMID 33178181, 2020). "In the context of infectious disease, many studies have further shown that IL-33/ST2 activity displays context-dependent protection and exacerbation of infection dependent on multiple factors, including the infectious agent, cellular microenvironment, and affected organs." (PMID 32363166, 2020). "The CCP1/2 truncation mutant of HpARI was shown to amplify rather than suppress IL-33 responses in vitro and in vivo, in a range of cytokine-, allergen-, and infection-driven systems." (PMID 33351862, 2020). "However, IL-33 and ST2 were less expressed at the basal level and during infection in B6 wt mice, compared to BALB/c wt mice." (PMID 32571430, 2020). "In the absence of IL-33 signaling during infection, approximately one-third fewer total T cells were present in the brain by flow cytometry, suggesting an inability to recruit or maintain these cells." (PMID 33108405, 2020). "IL-33-mediated protection was not restricted to hypervirulent R20291 infection as IL-33 treatment robustly protected against the non-ribotype 027 C." (PMID 31221971, 2019). "Caspase-1 inactivates IL-33, and therefore, IL-33 is not produced when cells are activated to form an inflammasome by infection with bacteria harboring TLR ligands." (PMID 30717382, 2019). "In addition, previous study showed the upregulation of IL-33 produced by HIV-1 clade B infected cells in comparison to clade C, under identical in vitro infection levels." (PMID 30564243, 2018). "However, soluble ST2 (sST2), a decoy receptor of IL-33, was also increased in early HIV infected patients, especially in those with progressive infection." (PMID 30564243, 2018). "Various, even negative biofunctions of IL-33 pathways have now been widely verified in pathogenesis among immunological mechanisms, like Th2-related immune-stimuli, inflammation/infection-induced tissue protectors." (PMID 30619376, 2018). "We reported earlier that the overall expression of Il33 mRNA was not significantly altered in the brain of wild-type (WT) C57BL/6 mice during ECM after PbA-infection." (PMID 28448579, 2017). "Regarding TH1 cytokines, IL-2 was not induced in WT or IL-33 KO mice after L2-MHV3 infection at mRNA level in the liver, neither at protein level in mouse sera (data not shown)." (PMID 28607531, 2017). "The proportion of hippocampal OLIG2+ IL-33+ cells was sharply increased on day 7 post PbA-infection in WT mice, but not in ST2-/- infected mice." (PMID 28448579, 2017). "Short term memory was reduced 5 days after PbA-infection in WT mice, while the cognition process remained unaltered in the absence of IL33/ST2 pathway." (PMID 28448579, 2017). "Therefore, it appears that eosinophil survival is promoted by extrinsic (LPS) and intrinsic (IL-33) danger signals particularly under conditions of low IL-5 concentrations as it may occur in certain anatomical sites where eosinophils get recruited during infection or tissue injury." (PMID 27690378, 2016). "Protection was associated with increased pulmonary type 2 cytokines IL-4 and IL-13 but not IL-33 at day 5 post infection." (PMID 26900854, 2016).
infection (continued). "Here, the absence of ST2 (the receptor for IL-33) following the infection with an encephalitogenic virus leads to increased cellular-mediated immunopathology on mouse CNS." (PMID 27334012, 2016). "The absence of IL-33 signaling during lethal infection attenuated cellular and tissue damage and delayed the onset of disease (i.e. weight loss), although such changes were not sufficient to rescue the mice from death." (PMID 26943125, 2016). "Appreciable IL-33 was detected among high-dose infection groups, rather than in samples infected with 3 MOI and control samples." (PMID 26943125, 2016). "IL-33-mediated protection was achieved when the cytokine was given relatively early after infection and delaying treatment by 48 h failed to control the disease." (PMID 25659095, 2015). "Infection with UV-irradiated RV did not elicit an IL-33 response, suggesting that RV-induced IL-33 is replication dependent." (PMID 26318341, 2015). "IL-33 was not produced by either Mph subset 8–16 h after mock-infection, Udorn-infection or LPS stimulation (data not shown)." (PMID 22238612, 2012). "This implies that TSLP is not likely to beimportant in conditioning the dermal immune response in our multiple infection model butdoes not rule out other cytokines such as IL-25 or IL-33 recently described to beimportant for Th2 induction." (PMID 21445234, 2011). "Notably, the lack of response to IL-33 in terms of trTreg expansion was specific to the infection condition, as this cytokine increased trTregs in non-infected animals." (PMID 39883714, 2025). "Mechanical injury, infection, inflammatory cytokines and proteases such as trypsin and papain stimulate the release of various cytokines of epithelial origin, such as thymic stromal lymphopoietin (TSLP), interleukin-25 (IL-25), interleukin-33 (IL-33) and periostin." (PMID 40981017, 2025). "The proportion of IgG3 was increased in IL-33-treated mice with or without infection." (PMID 38787044, 2024). "However, IL-33 can also be actively released from IECs in the absence of cell death during infection." (PMID 39559705, 2024). "Given our negative findings regarding roles for lymphocytes in this process, as well as recent work highlighting a role for IL-33 signaling in microglial activation we sought next to characterize the role of IL-33 on microglial activation following intracranial WNV-E218A infection." (PMID 37983247, 2023). "Notably, IL-33, TGFα, and IL-18 were depleted in end of infection samples compared with the negative controls, indicating a difference in cytokine profile between resolving infection and baseline innate immune status." (PMID 36586415, 2023). "By analyzing the response of epithelial cells, the authors showed that the transformed murine respiratory epithelial cell line, MLE-15, presented a threefold increase in IL-33 mRNA expression after infection with influenza A virus compared with non-infected cells." (PMID 35327516, 2022). "Taken together, these results indicate that IL-33-induced excessive generation of mTEC IV cells (thymic tuft cells) contributes to the disruption of TEC compartment by changing the ratio of mTEC/cTEC and subsequent thymus involution-mediated T cell aging during severe infection." (PMID 36371464, 2022). "In summary, Tregs seem not to drive the enhanced pathology induced by IL-33 during CR infection." (PMID 33654214, 2021). "Interestingly, IL-33 was highly abundant in the colon under steady-state, and Il33 transcripts and IL-33 protein were slightly but not significantly increased at day 10 post infection." (PMID 33654214, 2021). "Thus, the specific accumulation of ST2-expressing Tregs induced by IL-33 is not responsible for the uncontrolled pathogen dissemination and severe disease progression during CR infection." (PMID 33654214, 2021).
infection (continued). "The mechanisms for the release of IL-33 have not been fully elucidated; however, in addition to infection or cell damage, contact with allergens that activate pattern recognition receptors (PRRs) on the surface of epithelial cells may be a trigger." (PMID 33615121, 2021). "Mast cells release IL-25 and IL-33 in response to H. polygyrus-induced release of ATP from epithelial cells and mast cell-derived IL-33 induces ILC2 production of IL-13: both events have the potential to drive ETC hyperplasia as a response to infection with helminth parasites." (PMID 34578195, 2021). "However, we could not rule out that there may be other unidentified molecules, other than IL-33, that could bind to ST2 receptors to induce neutrophil migration during the early phase of infection." (PMID 34638904, 2021). "Several organs and tissues other than the lung and immune cells, namely the heart, adipose tissue and endothelium, express locally the IL-33/ST2 axis and may release sST2, as a consequence of direct infection by SARS-CoV-2 or secondary to immune system activation." (PMID 34441830, 2021). "The response induced by AXPN was localized to the site of infection, as treatment did not alter gene expression in the mesenteric lymph nodes of mice and IL-33 could not be detected in serum by ELISA (data not shown)." (PMID 32156806, 2020). "While IL-33+ cells were mainly located in the GC at basal level and during infection, ST2+ cells were found in the red pulp and increased both in the red pulp and the marginal zone during infection, suggesting an influx or activation of both myeloid and lymphoid cells." (PMID 32571430, 2020). "Notably, we identified that infection with H. polygrus was able to suppress EAE in an IL-Rα-dependent manner, with further evidence to suggest that a lack of IL-4 signaling also ablates any disease protection mediated through the IL-33/ST2 receptor." (PMID 33117327, 2020). "Thus, IL-33 treatment did not significantly alter the microbiota composition prior to infection with C. difficile." (PMID 31221971, 2019). "However, in line with the CTL-boosting role of IL-33 in primary LCMV infections, circulating memory CTLs required IL-33 for efficient secondary expansion, enhanced effector functions, and virus control upon challenge infection." (PMID 31447845, 2019). "Notably, compared with no infection or infection with ΔcagA-strain, WT H. pylori-strain-infected human primary gastric epithelial cells were also able to potently increase IL-33 production." (PMID 29691371, 2018). "Our results showed that topical LTB4 decreased lesion size and bacterial clearance in macrophage-depleted mice, restored production of the chemokines, CCL2 and CXCL4, but not CXCL2, VEGF, IL-33, and IL-1β and neutrophil migration to the site of infection in DT-treated MMDTR mice." (PMID 30102746, 2018). "For example, IL1-β (gene IL1B) and IL23, which were markedly induced by Mtb in our infection model, are known to induce group 3 ILC (ILC3); IL15 among others activates ILC1 cells, and IL1-β, thymic stromal lymphopoietin (TSLP) and IL33 are prominent activators of ILC2 cells." (PMID 29977236, 2018). "The immunostaining of liver tissues revealed that IL-33 was initially expressed only in the sinusoidal and vascular endothelial cells in the liver of control WT mice (brown staining in PBS condition) and induced in the nuclei of hepatocytes during L2-MHV3 infection (48 h and 72 h PI) (arrow)." (PMID 28607531, 2017). "Interestingly, PbA-infection induced microglia activation and proliferation, even in the absence of functional IL-33/ST2 pathway." (PMID 28448579, 2017). "Moreover, exogenous IL-33 treatment did not affect the resistance of Stat6−/− mice to subsequent challenge infection with L. pneumophila." (PMID 28374774, 2017). "Thus microglia activation and proliferation 7 days post-infection was independent of the IL-33/ST2 pathway." (PMID 28448579, 2017).
infection (continued). "Here, we show a prominent production of IL-33 by essentially all oligodendrocytes (98%) in the hippocampus after PbA-infection, which does not formally exclude a contribution of the other IL-33 producing cells such as astrocytes, and this was dependent on the IL-33/ST2 pathway." (PMID 28448579, 2017). "Similarly, to our previous results, infection with live P. aeruginosa led to an increase in IL-33 mRNA in a CFTRdelF508 AEC line but not in its wild type counterpart." (PMID 26793709, 2015). "Interestingly, the increased mRNA expression was accompanied by increased detection of intracellular but not extracellular IL-33 following a 6 h infection of CFTRdelF508 AECs with P. aeruginosa." (PMID 26793709, 2015). "Using cells only treated with IL-33 or cells only infected with HTNV as controls, the mRNA expression of IL-1β, IL-6, IL-8, CCL2, CCL20, CXCL1, CXCL2, and CX3CL1 was significantly induced in HUVECs prior to infection with HTNV (MOI = 1) for 48 h and then exposed to IL-33 (20 ng/ml) for 6 h." (PMID 25658420, 2015). "However, administration of IL-33 at a chronic stage of infection did not improve resistance to T. spiralis." (PMID 24663956, 2014). "Based on these findings, we speculate that IL-33 may function, similarly to the prototype ‘alarmin’ HMGB1, as an endogenous ‘danger’ signal to alert the immune system after endothelial or epithelial cell damage during trauma or infection." (PMID 18836528, 2008). "An intriguing possibility is that IL-33, which exhibits chemotactic properties for Th2 lymphocytes, may modulate migration of Th2 lymphocytes through HEV walls and FRC networks within T-cell areas in lymph nodes during infection." (PMID 18836528, 2008). "IL-33 could act alone or in concert with other mediators, such as thymic stromal lymphopoietin (TSLP), which is also expressed by inflamed skin and tonsillar crypt epithelium, and can be released by epithelial cells in response to trauma or infection." (PMID 18836528, 2008). "In a subsequent effort to modulate the trTreg response in vivo during acute infection, and considering the results from the previous section indicating that the Th1 responses emerging during infection may limit trTreg expansion, we opted to treat INF mice with IL-33 on 0, 3, and 6 dpi." (PMID 39883714, 2025). "Furthermore, inhibition of the ST2/IL-33 pathway and subsequent dampening of the downstream MyD88/MAPK/NF-κB inflammatory pathways may prevent the secretion of cytokines from immune cells, potentially impacting infection response." (PMID 41163220, 2025). "Importantly, we also observe a reduction in GFAP+IL-33+ cells post-infection, and while our genetic studies support a role for oligodendrocyte-derived IL-33 in this setting, our work does not formally rule out a contribution of IL-33 derived from astrocytes in this model." (PMID 37983247, 2023). "Thus, it is understandable that the absence of IL-33 in IL-33−/− mice at the early stage of the patent infection might have left ILC2 inactivated, leading to impaired type 2 immunity, as seen in the present study." (PMID 33482904, 2021). "The lack of IL-33 induction in humans may explain why the infection persists." (PMID 34662329, 2021). "Also, these increased levels of IL-33 in serum were found to peak around the 8th week of infection in mice, corresponding to the peak of egg-induced immune responses, suggesting that through their ESP, eggs may be the main inducers of IL-33 release in schistosome infections." (PMID 33482904, 2021). "To assess whether a lack of IL-33 during priming affects the formation of memory CTLs, we adoptively transferred LCMV-specific CD8+ T cells (P14 cells) either into WT or IL-33-deficient primary recipient mice, followed by infection with 200 PFU LCMV." (PMID 31447845, 2019).